BSN (bassoon presynaptic cytomatrix protein)
Description:
Scaffold protein of the presynaptic cytomatrix at the active zone (CAZ) which is the place in the synapse where neurotransmitter is released. After synthesis, participates in the formation of Golgi-derived membranous organelles termed Piccolo-Bassoon transport vesicles (PTVs) that are transported along axons to sites of nascent synaptic contacts. At the presynaptic active zone, regulates the spatial organization of synaptic vesicle cluster, the protein complexes that execute membrane fusion and compensatory endocytosis (By similarity). Also functions in processes other than assembly such as the regulation of specific presynaptic protein ubiquitination by interacting with SIAH1 or the regulation of presynaptic autophagy by associating with ATG5 (By similarity). Also mediates synapse to nucleus communication leading to reconfiguration of gene expression by associating with the transcriptional corepressor CTBP1 and by subsequently reducing the size of its pool available for nuclear import (By similarity). Inhibits the activity of the proportion of DAO enzyme that localizes to the presynaptic active zone, which may modulate synaptic transmission (By similarity).
Synonyms: ZNF231
Tractability: Antibody: UniProt places it where antibodies can reach, with medium confidence. PROTAC: ubiquitination databases record sites on it; its protein half-life has been measured.
Gene: Protein-coding gene on chromosome 3 (49,554,477 to 49,671,549, forward strand). Ensembl gene ENSG00000164061.
Subcellular location: Cytoplasm; Presynaptic active zone; Cytoplasm, cytoskeleton; Cytoplasmic vesicle, secretory vesicle, synaptic vesicle membrane
Pathways (Reactome):
Sensory Perception: Sensory processing of sound by inner hair cells of the cochlea
Gene Ontology:
Molecular function: enzyme inhibitor activity; structural constituent of presynaptic active zone; metal ion binding
Biological process: chemical synaptic transmission; modulation of chemical synaptic transmission; presynaptic active zone assembly; protein localization to synapse; maintenance of presynaptic active zone structure; regulation of synaptic vesicle cycle; synaptic vesicle clustering
Cellular component: axon; cytoplasm; cytoskeleton of presynaptic active zone; dendrite; excitatory synapse; GABA-ergic synapse; glutamatergic synapse; nucleus; presynaptic active zone; synaptic vesicle; cell surface; cochlear hair cell ribbon synapse; cytoskeleton; neuron projection terminus; organelle; postsynaptic density; presynapse; Schaffer collateral - CA1 synapse; synapse; synaptic vesicle membrane
Genetic constraint (gnomAD): Loss-of-function variants: 56 observed, 258.16 expected, observed/expected ratio (o/e) 0.22, 90% interval 0.17 to 0.27. The upper end of that interval is the gene's LOEUF score, 0.27, which puts it in group 1 of 6, group 1 being the genes least tolerant of losing a copy. Missense variants: 4,614 observed, 5,276.7 expected, observed/expected ratio (o/e) 0.87, 90% interval 0.85 to 0.9. Synonymous variants: 2,057 observed, 2,169.3 expected, observed/expected ratio (o/e) 0.95, 90% interval 0.91 to 0.98.
Homologues: Orthologues: chimpanzee BSN (99% identical), macaque BSN (92% identical), dog BSN (89% identical), mouse Bsn (89% identical), rat Bsn (89% identical), pig BSN (87% identical), guinea pig BSN (85% identical), tropical clawed frog bsn (55% identical), zebrafish bsnb (40% identical), zebrafish BSN (27% identical), Caenorhabditis elegans cla-1 (21% identical). Paralogues in human: PCLO (32% identical).
Diseases named in the same sentence as BSN in open-access papers:
BSN is named in the same sentence as 38 diseases in open-access papers, as found by Europe PMC text mining. Sharing a sentence is not in itself a finding about the gene and the disease. The quoted sentences say what the papers report.
Obesity (6 papers, 2023 to 2025). Accumulation of substantial excess body fat. "Variants in BSN were associated with markedly increased obesity risk, even surpassing that of well-known monogenic obesity genes such as MC4R." (PMID 41009961, 2025). "We have identified a gene, BSN, for which we have demonstrated an association of rare pLoF variants with obesity in two independent large cohorts: the UKBB and All of Us, with similarly large effect size." (PMID 37865656, 2023). "The impact of common genetic risk factors for obesity was stronger in individuals with BSN variants, suggesting that these rare mutations may intensify the effects of broader genetic susceptibility." (PMID 41009961, 2025). "Analyses of whole-exome sequencing data identify rare loss-of-function variants in BSN associated with adult-onset obesity, type 2 diabetes and fatty liver disease, with stronger effect sizes than those observed for variants in known obesity risk genes such as MC4R." (PMID 38575728, 2024). "Heterozygous pLoF BSN variants constitute a new etiology for obesity." (PMID 37865656, 2023). "Rare PTVs in APBA1 and BSN appear to preferentially confer risk of adult-onset obesity, which we propose might be due to widespread dysregulation of neurodevelopment, neurogenesis and neuronal oxidative phosphorylation in neurons within the central feeding circuitry." (PMID 38575728, 2024). "However, as the common genetic susceptibility to obesity is thought to act predominantly via central regulation of food intake, we hypothesize that BSN may have widespread involvement in neurodevelopment and neurogenesis, with BSN variants leading to increased appetitive drive." (PMID 38575728, 2024). "Furthermore, loss-of-function variants in BSN and APB1A have demonstrated markedly larger effects on obesity risk than those observed for variants in MC4R." (PMID 40523925, 2025). "Therefore, APBA1 and BSN appear to be among the few genetic determinants of predominantly adult-onset obesity." (PMID 38575728, 2024). "In contrast to almost all previously reported obesity-associated genes, neither BSN nor APBA1 showed any association with childhood body size or puberty timing (P > 0.05), suggesting adult-onset effects on body weight based on the phenotypes available in UK Biobank." (PMID 38575728, 2024). "The links identified here with predominantly adult-onset obesity may be consistent with the putative roles of APBA1 and BSN in aging-related neurosecretory vesicle dysfunction and neurodegeneration." (PMID 38575728, 2024).
epilepsy (4 papers, 2013 to 2025). A brain disorder characterized by episodes of abnormally increased neuronal discharge resulting in transient episodes of sensory or motor neurological dysfunction, or psychic dysfunction. "The BSN gene, which encodes the presynaptic scaffolding protein Bassoon, has been increasingly recognized for its association with epilepsy and broader neurodevelopmental disorders." (PMID 41033923, 2025). "Arginase deficiency has previously been shown to promote tissue lipid accumulation via enhanced de novo lipogenesis independent of systemic metabolic changes, suggesting that BSN mutations may drive a cholesterol–arginase imbalance as a mechanistic contributor to epilepsy." (PMID 41033923, 2025). "This underscore BSN, BDNF and NTRK2 interconnection in epilepsy, corroborated in this study." (PMID 24278214, 2013). "Although BSN has not been implicated in ASD, an association with epilepsy has been suggested." (PMID 39610113, 2025).
endometriosis (3 papers, 2024 to 2025). The growth of functional endometrial tissue in anatomic sites outside the uterine body. "The clustering analysis, which reveals pain-related genes (SRP14/BMF, GDAP1, MLLT10, BSN, and NGF), further solidifies the genetic basis for the chronic and often debilitating pain experienced by patients with endometriosis." (PMID 41516028, 2025). "eQTL analyses highlighted genes affected by shared risk variants, enriched for seven pathways across all four conditions, with three genetic loci shared between endometriosis and osteoarthritis (BMPR2/2q33.1, BSN/3p21.31, MLLT10/10p12.31) and one with rheumatoid arthritis (XKR6/8p23.1)." (PMID 40262193, 2025).
Alzheimer disease (2 papers, 2018 to 2022). A progressive, neurodegenerative disease characterized by loss of function and death of nerve cells in several areas of the brain leading to loss of cognitive function such as memory and language. "We identified Bassoon (BSN), a presynaptic scaffolding protein, as an interactor of the tau seed isolated from a mouse model of tauopathy, and from Alzheimer’s disease and progressive supranuclear palsy postmortem samples." (PMID 36344699, 2022). "Furthermore, Western blot analysis of a freshly frozen sample of the frontal cortex revealed phosphorylated tau triplet bands (60, 64, and 68 kDa) (arrow) similar to those observed in patients with Alzheimer’s disease and did not reveal a decrease in BSN expression." (PMID 29339765, 2018).
endometrial cancer (2 papers, 2019 to 2021). Primary or metastatic malignant neoplasm involving the endometrium (mucous membrane that lines the endometrial cavity). "BSN mutations are associated with endometrial cancer prognosis." (PMID 34660294, 2021).
multiple system atrophy (2 papers, 2023 to 2024). Multiple system atrophy (MSA) is a neurodegenerative disorder characterized by autonomic failure (cardiovascular and/or urinary), parkinsonism, cerebellar impairment and corticospinal signs with a median survival of 6-9 years. "Furthermore, rare predicted-damaging missense mutations in BSN have been reported in four patients with progressive supranuclear palsy-like syndrome with features of multiple system atrophy and Alzheimer disease." (PMID 38575728, 2024). "BSN is expressed primarily in the brain and is reportedly upregulated in the frontal lobes of patients with multiple system atrophy, a progressive neurodegenerative disease." (PMID 38575728, 2024). "BSN was originally identified while attempting to identify expressed cerebellar transcripts in patients with multiple system atrophy, a rare progressive neurodegenerative disease characterized by cerebellar symptoms, parkinsonism, and autonomic dysfunction." (PMID 37865656, 2023).
osteoarthritis (2 papers, 2022 to 2025). A noninflammatory degenerative joint disease occurring chiefly in older persons, characterized by degeneration of the articular cartilage, hypertrophy of bone at the margins and changes in the synovial membrane. "We identified methylation sites that play a putative causal role in osteoarthritis, for example for the WWP2, BSN, and MFHAS1 genes." (PMID 35679866, 2022). "Specifically, three SNPs were shared with osteoarthritis (BMPR2/2q33.1, BSN/3p21.31, and MLLT10/10p12.31), and one was shared with both osteoarthritis and rheumatoid arthritis (XKR6/8p23.1)." (PMID 40262193, 2025).
tauopathies (2 papers, 2022 to 2024). "Overall, these studies suggest associations among BSN, neurodegenerative events and tau pathology, and support the feasibility of BSN downregulation as a therapeutic avenue for neurodegenerative tauopathies." (PMID 36344699, 2022). "We show that BSN exacerbates tau seeding and toxicity in both mouse and Drosophila models for tauopathy, and that BSN downregulation decreases tau spreading and overall disease pathology, rescuing synaptic and behavioral impairments and reducing brain atrophy." (PMID 36344699, 2022). "Furthermore, BSN downregulation decreases tau spreading and rescues synaptic and behavioral impairment in a mouse model of tauopathy." (PMID 36344699, 2022). "We then confirmed by co-IP that, in both tauopathies, BSN interacts with tau in fraction 9 but does not interact with tau in fraction 9 from age-matched controls." (PMID 36344699, 2022).
bipolar disorder (1 paper, 2021). A disorder of the brain that causes unusual shifts in mood, energy, activity levels and the ability to carry out day-to-day tasks. "The molecular mechanisms underlying schizophrenia and bipolar disorder of these three rare mutations of BSN and PCLO identified in this study remain to be elucidated." (PMID 34834409, 2021). "Our results increase the genetic and allelic heterogeneity of schizophrenia and bipolar disorder and suggest that BSN and PCLO may be considered risk genes for schizophrenia and bipolar disorder." (PMID 34834409, 2021). "We report the identification of three private rare pathogenic mutations of BSN and PCLO in three families with schizophrenia and bipolar disorder, respectively." (PMID 34834409, 2021). "In conclusion, we identified three private rare pathogenic mutations in two PCM genes, BSN and PCLO, in three families with schizophrenia and bipolar disorder." (PMID 34834409, 2021).
breast carcinoma (1 paper, 2021). "BSN transcripts were most abundant in NCI-H1930, OCI-Ly3, SUDHL1 (all non-Hodgkin’s lymphoma) and AU65 (breast cancer)." (PMID 33836029, 2021).
Crohn disease (1 paper, 2017). A gastrointestinal disorder characterized by chronic inflammation involving all layers of the intestinal wall, noncaseating granulomas affecting the intestinal wall and regional lymph nodes, and transmural fibrosis. "Two independent signals were identified on chromosome 3, one of which was within Bassoon Presynaptic Cytomatrix Protein (BSN), a gene that encodes a scaffold protein expressed in the brain, is involved with neurotransmitter release and was previously associated with Crohn’s disease." (PMID 27864402, 2017).
dementia (1 paper, 2015). Loss of intellectual abilities interfering with an individual's social and occupational functions. "Furthermore, additional proteins which were consistently altered in both the FLNC-, GRN- and VCP-unique datasets, e.g. GFAP, NPTN, DBI, PRDX6, MARCKS and BSN, are closely associated with cognitive function, dementia and pathological aging." (PMID 26555887, 2015).
glioma (1 paper, 2021). A benign or malignant brain and spinal cord tumor that arises from glial cells (astrocytes, oligodendrocytes, ependymal cells). "The interaction between PART1-hsa-mir-25-SLC12A5/TACC2/BSN/TLN2/ZDHHC8 is largely unclear in glioma and requires further analysis." (PMID 34660294, 2021). "SLC12A5/TACC2/BSN/TLN2/ZDHHC8 was downregulated in patients with glioma with poor OS." (PMID 34660294, 2021).
hippocampal atrophy (1 paper, 2018). "The findings of severe hippocampal atrophy in the Japanese PSP-like family agree with those in the BSN mutant mice." (PMID 29339765, 2018).
multiple sclerosis (1 paper, 2023). A progressive autoimmune disorder affecting the central nervous system resulting in demyelination. "A recent study found that neuroinflammation leads to the induction and toxic accumulation of the synaptic protein BSN in the neuronal somata of mice and patients with multiple sclerosis, implying that BSN may contribute to neurodegeneration." (PMID 38250258, 2023).
schizophrenia (1 paper, 2021). A major psychotic disorder characterized by abnormalities in the perception or expression of reality. "To the best of our knowledge, we are the first to report the BSN missense mutation in patients with schizophrenia." (PMID 34834409, 2021). "In this study, we identified a rare missense mutation (R1087Q) of BSN in a multiplex family of schizophrenia that consisted of seven patients, including the affected father and his six affected children." (PMID 34834409, 2021). "The detection of R1087Q of BSN in the schizophrenia family suggests that BSN might be a risk gene for schizophrenia." (PMID 34834409, 2021). "We suggest that mutations of BSN may have pleiotropic clinical effects, and schizophrenia may be one of the clinical manifestations of BSN mutations." (PMID 34834409, 2021).
uterine disorder (1 paper, 2024). A non-neoplastic or neoplastic disorder that affects the uterine corpus or the cervix. "The uterine disorders cluster (two) was significantly associated with six loci, WNT4, GREB1, BSN, SYNE1, GDAP1, and ASTN2." (PMID 39315247, 2024). "Conversely, the BSN gene, although not statistically significant, demonstrated greater significance in the pain, uterine disorders, and pregnancy complications clusters, indicating a possible link to neurovascular or inflammatory mechanisms that could exacerbate these conditions." (PMID 39315247, 2024).
cancer (4 papers, 2019 to 2023). A tumor composed of atypical neoplastic, often pleomorphic cells that invade other tissues. "Transcript expression patterns for SHANK1, UBR3, and BSN in cancer cell lines and Clontech’s normal human tissue panels were analysed using qPCR, detection of the exon encoding the cross-reactive peptide." (PMID 33836029, 2021). "In PCa, BSN was involved in regulating cell apoptosis in cancer cells." (PMID 31787999, 2019).
neurodegenerative disease (4 papers, 2021 to 2024). A disorder of the central nervous system characterized by gradual and progressive loss of neural tissue and neurologic function. "Rare missense mutations of BSN have been reported to cause progressive supranuclear palsy-like syndrome, a rare neurodegenerative disease." (PMID 34834409, 2021). "Patients with multiple system atrophy, a rare progressive neurodegenerative disease, have been found to have increased BSN transcript expression in their postmortem brains compared to controls." (PMID 34834409, 2021).
tumor (2 papers, 2021 to 2022). "We observed nonsilent SNVs or indels in USP8, BSN and SLC35G5 in 1.9, 1.7 and 1.4% of tumours respectively." (PMID 34753926, 2021).
BSN also shares sentences with these, for which no sentence is quoted: ovarian carcinoma (2 papers); Parkinson disease (2); progressive supranuclear palsy (2); type 2 diabetes (2); Adult onset (1); Autoimmunity (1); Brain atrophy (1); brain injury (1); Cognitive impairment (1); Depression (1); fatty liver disease (1); melanoma (1); microtia (1); non-Hodgkin lymphoma (1); Onset (1); Parkinsonism (1); rheumatoid arthritis (1); type 2 diabetes mellitus (1).